LSR (lipolysis stimulated lipoprotein receptor)
Description:
Probable role in the clearance of triglyceride-rich lipoprotein from blood. Binds chylomicrons, LDL and VLDL in presence of free fatty acids and allows their subsequent uptake in the cells (By similarity). Maintains epithelial barrier function by recruiting MARVELD2/tricellulin to tricellular tight junctions (By similarity).
Synonyms: ILDR3; LISCH7
Tractability: Antibody: UniProt places it where antibodies can reach, with high confidence; its Gene Ontology location is reachable by antibodies, with high confidence; UniProt predicts a signal peptide or a membrane-spanning region; the Human Protein Atlas places it where antibodies can reach. PROTAC: UniProt records ubiquitination sites on it; ubiquitination databases record sites on it; its protein half-life has been measured.
Gene: Protein-coding gene on chromosome 19 (35,248,330 to 35,267,967, forward strand). Ensembl gene ENSG00000105699.
Subcellular location: Cell membrane; Cell junction, tight junction
Subcellular location (Human Protein Atlas): Cell Junctions; Plasma membrane
Pathways (Reactome):
Transport of small molecules: LDL clearance; VLDL clearance
Gene Ontology:
Biological process: epithelial structure maintenance; establishment of blood-brain barrier; establishment of skin barrier; liver development; maintenance of blood-brain barrier; protein localization to tricellular tight junction; tricellular tight junction assembly
Cellular component: cell junction; extracellular exosome; plasma membrane; tight junction; tricellular tight junction; bicellular tight junction
Genetic constraint (gnomAD): Loss-of-function variants: 43 observed, 57.77 expected, observed/expected ratio (o/e) 0.74, 90% interval 0.58 to 0.96. The upper end of that interval is the gene's LOEUF score, 0.96, which puts it in group 4 of 6, group 1 being the genes least tolerant of losing a copy. Missense variants: 898 observed, 801.87 expected, observed/expected ratio (o/e) 1.12, 90% interval 1.06 to 1.18. Synonymous variants: 389 observed, 332.82 expected, observed/expected ratio (o/e) 1.17, 90% interval 1.08 to 1.27.
Homologues: Orthologues: chimpanzee LSR (99% identical), macaque LSR (95% identical), pig LSR (86% identical), dog LSR (85% identical), guinea pig LSR (82% identical), rat Lsr (82% identical), rabbit LSR (82% identical), mouse Lsr (78% identical), tropical clawed frog lsr (54% identical), zebrafish lsr (45% identical). Paralogues in human: ILDR2 (35% identical), ILDR1 (23% identical).
Diseases named in the same sentence as LSR in open-access papers:
LSR is named in the same sentence as 51 diseases in open-access papers, as found by Europe PMC text mining. Sharing a sentence is not in itself a finding about the gene and the disease. The quoted sentences say what the papers report.
breast cancer (10 papers, 2014 to 2025). A primary or metastatic malignant neoplasm involving the breast. "In contrast to these publications, other studies demonstrated that LSR was overexpressed in breast and gastric cancers and that overexpressed LSR in breast cancer cells causes the development of cancer in xenograft studies." (PMID 35586495, 2022). "Similar to high CD44 levels, increased expression of LSR has been associated with altered gene expression of pathways involved in transformation and tumorigenesis, enhanced proliferation, survival in anchorage independent conditions and promotion of collective cell migration in breast cancer cells." (PMID 24990559, 2014). "Our recent findings revealed that lipolysis-stimulated lipoprotein receptor (LSR) is overexpressed in breast cancer patients." (PMID 41040511, 2025). "It was reported that overexpression of LSR in Hs578t cells, a claudin-low breast cancer cell line, enhances cell growth, invasion, and anchorage-independent growth." (PMID 41183038, 2025). "Triacylglycerol-rich lipoproteins are also metabolized by the cell surface protein LSR, which is highly expressed in breast cancer." (PMID 33413672, 2021). "According to Yang and colleagues, LSR is one of the most up-regulated genes related to development of visible metastasis in a mouse mammary tumor model." (PMID 27391068, 2017). "For instance, LSR is one of the most up-regulated genes related to development of visible metastasis in a mouse mammary tumor model." (PMID 27391068, 2017). "Treatment of 14 breast cancer cell lines revealed that LSR+/CD44- lines were highly sensitive, LSR+/CD44+ lines were slightly sensitive, and LSR-/CD44+ lines were resistant to iota cytotoxicity." (PMID 24990559, 2014). "Overexpression of LSR in claudin-low breast cancer cell lines re-established a family of TJ protein expression, thereby reverting claudin-low lines to other intrinsic breast cancer molecular subtypes." (PMID 24637461, 2014). "Herein, we sought to define the role of lipolysis stimulated lipoprotein receptor (LSR) in breast cancer and cancer cell behavior as LSR was recently correlated with tumor-initiating features." (PMID 24637461, 2014). "We demonstrate that LSR is the cell-surface protein that mediates iota toxin cytotoxicity through endocytosis in breast cancer cells, and propose a novel role for CD44 as a driver of resistance towards iota toxin via inhibition of endocytotic mechanisms." (PMID 24990559, 2014). "We recently demonstrated that LSR expression correlates with estrogen receptor positive breast cancers and that LSR signaling directs aggressive, tumor-initiating cell behaviors." (PMID 24990559, 2014). "As we show in this current study, iota toxin interacts with LSR to induce cell death and LSR expression is correlated with ERα-positive breast cancers." (PMID 24990559, 2014). "Overexpression of LSR in basal-like breast cancer cells promotes xenograft tumor development." (PMID 41183038, 2025). "Recent studies have reported that LSR downregulation inhibits cell proliferation and invasion in endometrial cancer, while its overexpression in gastric and breast cancers correlates with increased lipid uptake, cell proliferation, and cancer stem cell-like features." (PMID 41040511, 2025). "However, LSR’s role in breast cancer metabolism is complicated as it also regulates tight junctions and was recently identified to be capable of nuclear localization and DNA binding." (PMID 33413672, 2021). "In addition, LSR is the host receptor for the binary toxin Clostridium difficile transferase (CDT), and the potential for using CDT as a therapeutic vector targeting LSR has been investigated in breast cancer." (PMID 27036040, 2016). "Our data suggest that expression of LSR may direct collective cell migration and inhibit individual cell migration in breast cancer cells." (PMID 24637461, 2014). "We have previously shown a multifaceted role of LSR in directing breast cancer cell behavior." (PMID 24990559, 2014).
breast cancer (continued). "Given the emerging role of obesity and altered cellular metabolism in breast cancer, and the recent report highlighting the role of LSR in tumor initiating breast cancer cell populations, functional studies directly testing the role of LSR in breast cancer cell behavior were conducted." (PMID 24637461, 2014). "Collectively, these data show a direct role for LSR in promoting aggressive breast cancer behavior." (PMID 24637461, 2014). "From the perspective of a protein-based treatment tool, C. perfringens iota toxin is relatively unexplored yet possesses promising potential for targeting breast cancer, as recent evidence now implicates LSR and CD44 as functional facilitators of iota cytotoxicity." (PMID 24990559, 2014). "Collectively, these results underscore LSR as a promising therapeutic target for TNBC and potentially other breast cancer subtypes." (PMID 41040511, 2025). "In the present study, we investigated the role of LSR and CD44 in a tissue-specific manner by identifying which protein mediates the cytotoxic processes specific to breast cancer." (PMID 24990559, 2014). "However, while expression of LSR reduced the EMT phenotype in breast cancer cells, the high rate of proliferation, escape from anoikis, and the observed collective cell migration behaviors of LSR-containing cells suggests that tumors containing LSR may indeed display an aggressive cancer phenotype." (PMID 24637461, 2014). "The objective of the current study was to further characterize the roles of LSR and CD44 during C. perfringens iota cytotoxicity on breast cancer cells." (PMID 24990559, 2014). "Since LSR overexpression is more frequently detected in TNBC and basal-like breast cancer in particular, results from our models based on basal/TNBC cell lines could be a valuable reference for relevant studies." (PMID 41183038, 2025). "Collectively, these data suggest that expression of LSR and not CD44 is required for sensitivity of breast cancer cells to iota toxin." (PMID 24990559, 2014).
endometrial cancer (9 papers, 2016 to 2024). Primary or metastatic malignant neoplasm involving the endometrium (mucous membrane that lines the endometrial cavity). "LSR deficiency affects the malignancy of a variety of tumors, including bladder cancer, colon cancer, endometrial cancer, and head and neck cancer." (PMID 35463981, 2022). "In the present study, we first found that the loss of tricellular tight junction protein LSR promoted the invasion and migration of human endometrial cancer cells via upregulation of TEAD/AREG." (PMID 28071680, 2017). "To investigate how the loss of LSR induced cell migration, invasion and proliferation in the endometrial cancer cell line Sawano, we first performed DNA microarray analysis of Sawano cells transfected with the siRNA of LSR." (PMID 28071680, 2017). "It remains unclear how loss of transmembrane protein LSR enhances the cell migration, invasion and proliferation of endometrial cancer cells." (PMID 27036040, 2016). "However, the detailed intracellular signaling mechanisms by which the loss of LSR promotes cell invasion, migration and proliferation in endometrial cancer cells remain unknown." (PMID 28071680, 2017). "In contrast, previous work suggested that LSR is a type I transmembrane protein with extracellular N-terminus domain in mouse mammary epithelial cell line EpH4 and human endometrial cancer cell line Sawano cells." (PMID 39443717, 2024). "Loss of angulin-1/LSR affects the malignancy of various cancers, including bladder cancer, colon cancer, endometrial cancer, head and neck cancer and pancreatic cancer." (PMID 36961882, 2023). "Loss of angulin-1/LSR affects the malignancy of various cancers, including endometrial cancer, head and neck cancer and pancreatic cancer." (PMID 36961882, 2023). "Loss of angulin-1/LSR correlates with the malignancy in various cancers, including endometrioid-endometrial carcinoma (EEC)." (PMID 34944960, 2021). "The upregulation of LSR expression by these drugs contributed to the suppression of motility and invasion of endometrial cancer cells enhanced by leptin administration." (PMID 31330820, 2019). "Following knockdown of LSR in endometrial cancer Sawano cells, CLDN-1 expression increased, while there was no significant change in the expression levels of CLDN-3, -4, -7, and OCLN." (PMID 31330820, 2019). "In endometrial carcinoma G1, where the formation of gland-like structure is retained, the expression levels of tricellulin and LSR were distributed unevenly from the subapical to the lateral region of cell-cell junctions." (PMID 31330820, 2019). "More recently, we found that the expression of LSR in human endometrial cancer was decreased together with the malignancy and that the loss of LSR induced cell invasion, migration and proliferation in human endometrial cancer cell line Sawano16." (PMID 28071680, 2017). "The loss of LSR promoted cell invasion and migration via upregulation of TEAD1/AREG dependent on YAP/pYAP and AMOT/Merlin in human endometrial cancer cells." (PMID 28071680, 2017). "Very recently, it was reported also for the endometrial cancer cell line Sawano that LSR knockdown increased cell proliferation." (PMID 27391068, 2017). "In endometrial cancer which was diagnosed as the classic endometrial type I (endometrioid), LSR and AREG were highly expressed in some cancer cells that formed gland-like structures." (PMID 28071680, 2017). "In endometrial cancer tissues, downregulation of LSR and upregulation of AREG were observed together with malignancy, and Yes-associated protein (YAP) was present in the nuclei." (PMID 28071680, 2017). "Very recently, Shimada and colleagues reported that knockdown of LSR induced cell migration, invasion and proliferation in endometrial cancer cells." (PMID 27391068, 2017). "In the present study, in human endometrial cancer tissues, downregulation of LSR and upregulation of AREG were observed together with malignancy." (PMID 28071680, 2017).
endometrial cancer (continued). "Supportingly, a recent study reported for the endometrial cancer cell line Sawano that tricellulin relocalized from the tricellular region to the bicellular region at the membrane upon LSR knockdown." (PMID 27391068, 2017). "Taken together, our findings indicated that the loss of LSR promoted cell invasion and migration via upregulation of AREG dependent on YAP/pYAP and AMOT/Merlin in human endometrial cancer cells." (PMID 28071680, 2017). "We have also reported that downregulation of LSR promotes cell invasion via claudin-1-mediated MMPs in endometrial cancer cells." (PMID 28071680, 2017). "Taken together, the results of this study provide novel evidence that tTJ protein LSR negatively regulates cancer cell progression and development in endometrial cancer." (PMID 27036040, 2016). "Knockdown of LSR by the siRNA in cells of the endometrial cancer cell line Sawano, induced cell migration, invasion and proliferation, while TRIC relocalized from the tricellular region to the bicellular region at the membrane." (PMID 27036040, 2016). "Furthermore, downregulation of angulin-1/LSR promotes cell invasion via upregulation of CLDN-1-mediated MMPs in endometrial cancer cells." (PMID 36961882, 2023). "In vitro studies have shown that after LSR knockout, normal PDECs and endometrial cells of the epithelial barrier are damaged, and there is a significant increase in the migration, invasion, and proliferation of human pancreatic and endometrial cancer cells." (PMID 35463981, 2022). "The suppression of LSR downregulation may regulate the malignant transformation of endometrial cancer." (PMID 31330820, 2019). "The drugs for type 2 diabetes metformin and berberine enhanced LSR expression in endometrial cancer cells and normal HEEs and prevented the cell migration and invasion induced by downregulation of LSR in those treated with the siRNA or leptin in endometrial cancer cells." (PMID 27036040, 2016). "Furthermore, in the present study, downregulation of LSR by the siRNA and the leptin-treatment in endometrial cancer cells induced cell migration and invasion." (PMID 27036040, 2016). "Thus, it is possible that LSR may be a potential targeting molecule in therapy for endometrial cancer like clostridium perfringens enterotoxin (CPE)-mediated therapy targeting claudin-4." (PMID 27036040, 2016). "However, the effects of adipokines, metformin and berberine on the function and expression of LSR in normal tissues and endometrial cancer remain unclear, though LSR was originally cloned as a candidate lipoprotein receptor." (PMID 27036040, 2016). "Knockdown of LSR significantly induces Sp1 transcription factor activity in the CLDN-1 promoter region and promotes cell invasion via CLDN-1-mediated MMPs in endometrial cancer cells." (PMID 36961882, 2023). "Downregulation of angulin-1/LSR promotes cell invasion and migration via AMOT/Merlin in human endometrial cancer cells." (PMID 34944960, 2021). "In the present study, in endometrial cancer cells, upregulation of LSR by metformin via MAPK and upregulation of LSR via MAPK, PI3K and JAK2/STAT were observed." (PMID 27036040, 2016). "To study the roles and the regulation of LSR and TRIC in endometrial cancers in detail, we first investigated the expression and distribution of LSR and TRIC in endometrial cancer cell lines Sawano, HHUA, JHMUE-1 and JHMUE-2." (PMID 27036040, 2016). "It is possible that the antibody against N-terminal of angulin-1/LSR may be useful for therapy of endometriosis and endometrial cancer." (PMID 34944960, 2021). "Furthermore, LSR expression decreased and that of AREG increased in G2 and G3 endometrial cancers compared to G1." (PMID 28071680, 2017). "Furthermore, the expression of LSR and AMOT was decreased in G2 and G3 endometrial cancers compared to G1." (PMID 28071680, 2017). "Furthermore, angulin-1/LSR decreases and AREG increases in G2 and G3 of endometrial cancers." (PMID 34944960, 2021).
bladder cancer (4 papers, 2008 to 2022). "A study from Herbsleb and colleagues showed that RNAi-mediated knockdown of LSR in the bladder cancer cell line SW780 caused upregulation of gene networks implicated in cell growth and proliferation and thus to increased invasive cell behavior in a Matrigel-based invasion assay." (PMID 27391068, 2017). "In this study we have focused on the lipolysis stimulated lipoprotein receptor gene (LSR), which is differentially expressed in bladder cancer." (PMID 18647386, 2008). "A time course siRNA knock down experiment was performed to investigate the functional role of LSR in SW780 bladder cancer cells." (PMID 18647386, 2008). "An anti-oncogenic function of LSR was also observed in a study, which demonstrated that abolished LSR could increase the motility and invasion of bladder cancer cells." (PMID 35586495, 2022). "To investigate the function of LSR we used siRNA knockdown in the bladder cancer cell line SW780, which showed a high endogenous level of LSR expression." (PMID 18647386, 2008).
colon carcinoma (4 papers, 2017 to 2022). "Our study provides evidence that LSR affects epithelial morphology and barrier formation in CaCo-2 cells and examines for the first time the effects of LSR deficiency on the tumor growth properties of colon carcinoma-derived cell lines." (PMID 27391068, 2017). "Our study examines for the first time the effects of LSR deficiency on the tumor growth properties of colon carcinoma-derived cell lines." (PMID 27391068, 2017). "As proof-of-principle, we applied our new approach, denoted as CRISPA, to knock out lipolysis-stimulated lipoprotein receptor (LSR) in the human colon cancer cell line HCT116 and green-fluorescent protein (GFP) in human embryonic kidney 293T cells stably expressing GFP." (PMID 34733166, 2021).